SCARB2 (scavenger receptor class B member 2)
Diseases named in the same sentence as SCARB2 in open-access papers (continued):
Sharing a sentence is not in itself a finding about the gene and the disease.
tumor (8 papers, 2022 to 2025). "At the endpoint of inoculation days, the tumors generated from SCARB2 knockout tumor spheroids showed the decreased proportions of CD24, EpCAM, CD13, or CD133 positive cells." (PMID 37739936, 2023). "Here, the authors identify SCARB2 as a driver of tumour-initiating cells via enhanced MYC activity and evaluate the efficacy of targeting this interaction using an FDA approved drug, Polymyxin-B, in preclinical models of HCC." (PMID 37739936, 2023). "Knockout of Scarb2 in hepatocytes dramatically decreased the tumor sizes, liver weights, and tumor nodules in the DEN-induced hepatocarcinogenesis model." (PMID 37739936, 2023). "Tumor organoids with SCARB2 deletion showed a higher apoptosis ratio than their control counterparts when treated with sorafenib." (PMID 37739936, 2023). "SCARB2 knockout suppressed the proliferation, invasion and tumor initiation efficiency of HCC cells by reducing MYC transcriptional activity and acetylation." (PMID 37739936, 2023). "SCARB2 knockout in tumor spheroids resulted in significantly decreased tumor growth and reduced final tumor sizes and tumor weights." (PMID 37739936, 2023). "SCARB2 expression was enhanced in tumor compared to that in normal liver tissues and up-regulation of SCARB2 was observed in every stage of HCC." (PMID 37739936, 2023). "The limiting-dilution assays in vitro showed that the frequency of tumor-initiating cells capable of forming spheres decreased after SCARB2 knockout in HCC cells." (PMID 37739936, 2023). "Collectively, these data suggest that Scarb2 is essential for hepatocarcinogenesis and Scarb2 deletion reduces the tumor growth and metastasis." (PMID 37739936, 2023). "Our data also revealed that both of Th2 cytokine signature and SCARB2 expression in GBM patients fosters a tumor-promoting environment and might facilitates tumor growth." (PMID 41210942, 2025). "The proliferation and invasion of tumor organoids were decreased when SCARB2 was knocked down." (PMID 37739936, 2023). "Heterozygous knockout of Scarb2 decreased the tumor sizes and weights." (PMID 37739936, 2023). "Additionally, the proportion of CD24, EpCAM, CD13, or CD133 positive cells were reduced in SCARB2 knockout tumor organoids." (PMID 37739936, 2023). "Furthermore, even with heterozygous knockout of Scarb2, the tumor incidence rate decreased, and the survival time of CreAlbScarb2F/+Myc mice was extended based on Kaplan–Meier analysis." (PMID 37739936, 2023). "C3 subtype (inflammatory) is enriched in SCARB2 expressed LGG cells with the elevated Th17 and Th1 genes and tumor cell proliferation." (PMID 41210942, 2025). "Screening of a database of FDA (Food and Drug Administration)-approved drugs shows Polymyxin B displays high binding affinity for SCARB2 protein, disrupts the SCARB2-MYC interaction, decreases MYC activity, and reduces the tumor burden." (PMID 37739936, 2023). "In an established HCC patient-derived xenograft (PDX) model with positive expression of MYC and SCARB2, we observed that PMB suppressed the tumor growth and the combination of PMB and sorafenib further decreased the growth and weights of PDXs in mice." (PMID 37739936, 2023). "In addition, there is significant interaction between SCARB2 and immune subtype within the LGG tumor microenvironment." (PMID 41210942, 2025). "Although we identified SCARB2 positive cells account for about 10% of the heterogeneous primary HCC cells, whether SCARB2 positive cells in HCC are tumor initiating cells and drive the expansion of tumor cells with stem cell characteristics needed to be further verified." (PMID 37739936, 2023).
cancer (7 papers, 2022 to 2025). A tumor composed of atypical neoplastic, often pleomorphic cells that invade other tissues. "The expression levels of SCARB2 were significantly higher in the cancer tissues of GBM and LGG compared to the corresponding normal tissues." (PMID 41210942, 2025). "As TILs are promising components in immunotherapy for cancers, we further explored the correlation between abundance of TILs and SCARB2 level in LGG and GBM." (PMID 41210942, 2025). "We find that SCARB2 regulates cancer stem cell-like properties of HCC by enhancing MYC activity, which plays important role in promoting HCC initiation and progression." (PMID 37739936, 2023). "Here, we perform a metabolic gene CRISPR/Cas9 knockout library screen in tumorspheres derived from HCC cells and find that deletion of SCARB2 suppresses the cancer stem cell-like properties of HCC cells." (PMID 37739936, 2023). "However, the role of SCARB2 in cancer, especially HCC, remains uncharacterized." (PMID 37739936, 2023). "However, the relationship between SCARB2 and cancer has not yet been reported or validated." (PMID 37739936, 2023).
neurological diseases (6 papers, 2013 to 2022). "LIMP-2 mutations (SCARB2 gene) have been described in several neurological disorders." (PMID 28218669, 2017). "Interestingly, Scarb2 was found in the proteome of signaling endosomes, a class of organelles undergoing axonal retrograde transport, which is enriched in markers of neurological diseases." (PMID 35973377, 2022). "Furthermore, transgenic mice expressing human SCARB2 (SCARB2-Tg) are more susceptible to EV71 and developed neurological disorders following EV71 infection." (PMID 26181772, 2015). "Taking advantage of these findings, we had generated transgenic mice expressing Human SCARB2 (hSCARB2-Tg) and proved that hSCARB2-Tg mice have greater susceptibility and pathogenesis, induce both HFMD and neurological diseases upon infection with EV71 isolates of genotype B and C." (PMID 24098578, 2013). "However, human SCARB2 transgenic mice exhibit paralytic diseases after EVA71 inoculation via intracerebral, intravenous, and intraperitoneal routes, which—like the symptoms observed in humans infected with EVA71—suggests that SCARB2 is essential to EVA71-induced neurological diseases." (PMID 33298183, 2020).
neurodegenerative disease (4 papers, 2017 to 2024). A disorder of the central nervous system characterized by gradual and progressive loss of neural tissue and neurologic function. "Altogether, we reveal the role of SCARB2 in metabolism regulation besides the nervous system, which provides a theoretical basis for weight loss treatment of patients with neurodegenerative diseases." (PMID 35955761, 2022).
autosomal recessive disease (1 paper, 2011). Autosomal recessive form of disease. "The syndrome is considered to be an autosomal-recessive disease related to loss-of-function mutations in SCARB2 which encode a lysosomal-membrane type 2 protein, a member of the CD 36 scavenger receptor-like protein family." (PMID 22032306, 2011).
SCARB2 also shares sentences with these, for which no sentence is quoted: renal failure (4 papers); prostate carcinoma (3); synucleinopathies (3); bacterial infection (2); dilated cardiomyopathy (2); lysosomal storage disorder (2); Myoclonus (2); nephropathies (2); Pendred syndrome (2); Stroke (2); acute myeloid leukemia (1); Adrenal insufficiency (1); aphthous ulcers (1); Cognitive impairment (1); craniopharyngioma (1); demyelination (1); diabetes (1); end-stage renal failure (1); experimental autoimmune encephalomyelitis (1); Fabry disease (1); focal segmental glomerulosclerosis (1); fungal infection (1); generalized epilepsy (1); genetic disorder (1); GM2 gangliosidosis (1); hand-foot-mouth disease (1); head and neck squamous cell carcinoma (1); hearing loss (1); heart disease (1); heart failure (1).
A further 27 diseases each share a sentence with SCARB2 in 1 paper.